POFUT3 (protein O-fucosyltransferase 3)
Description:
Protein O-fucosyltransferase that specifically catalyzes O-fucosylation of serine or threonine residues in EMI domains of target proteins, such as MMRN1, MMRN2 and EMID1. Attaches fucose through an O-glycosidic linkage. O-fucosylation of EMI domain-containing proteins may be required for facilitating protein folding and secretion. May also show alpha-(1,3)-fucosyltransferase activity toward the innermost N-acetyl glucosamine (GlcNAc) residue in biantennary N-glycan acceptors. However, this was tested with a library of synthetic substrates and this activity is unsure in vivo. May be involved in biosynthesis of Lewis X-carrying biantennary N-glycans that regulate neuron stem cell self-renewal during brain development (By similarity).
Synonyms: FUT10; FUCTX
Tractability: Antibody: UniProt predicts a signal peptide or a membrane-spanning region. PROTAC: ubiquitination databases record sites on it.
Target class: Enzyme; Transferase
Gene: Protein-coding gene on chromosome 8 (33,370,824 to 33,473,146, reverse strand). Ensembl gene ENSG00000172728.
Subcellular location: Endoplasmic reticulum membrane; Endoplasmic reticulum membrane (Isoform 1); Golgi apparatus membrane; Golgi apparatus (Isoform 4); Lysosome; Endoplasmic reticulum membrane (Isoform 5)
Subcellular location (Human Protein Atlas): Endoplasmic reticulum; Golgi apparatus; Nucleoplasm
Pathways (Reactome):
Metabolism of proteins: O-linked glycosylation
Gene Ontology:
Molecular function: fucosyltransferase activity; peptide-O-fucosyltransferase activity; alpha-(1->3)-fucosyltransferase activity
Biological process: positive regulation of protein secretion; fertilization; glycoprotein biosynthetic process; hemopoiesis; L-fucose catabolic process; nervous system development; neuronal stem cell division; protein folding; protein O-linked glycosylation; protein targeting; wound healing; N-glycan processing
Cellular component: endoplasmic reticulum; endoplasmic reticulum membrane; Golgi apparatus; lysosome; Golgi membrane; membrane
Genetic constraint (gnomAD): Loss-of-function variants: 37 observed, 48.66 expected, observed/expected ratio (o/e) 0.76, 90% interval 0.58 to 1. The upper end of that interval is the gene's LOEUF score, 1, which puts it in group 4 of 6, group 1 being the genes least tolerant of losing a copy. Missense variants: 529 observed, 599.93 expected, observed/expected ratio (o/e) 0.88, 90% interval 0.82 to 0.95. Synonymous variants: 215 observed, 229.06 expected, observed/expected ratio (o/e) 0.94, 90% interval 0.84 to 1.05.
Homologues: Orthologues: chimpanzee FUT10 (96% identical), dog FUT10 (88% identical), guinea pig FUT10 (87% identical), pig FUT10 (85% identical), mouse Fut10 (82% identical), rabbit FUT10 (80% identical), rat Fut10 (79% identical), tropical clawed frog fut10 (65% identical), zebrafish fut10 (57% identical), Drosophila melanogaster FucTB (34% identical), Caenorhabditis elegans fut-3 (16% identical), Caenorhabditis elegans fut-4 (16% identical), and 9 more. Paralogues in human: POFUT4 (38% identical), FUT5 (19% identical), FUT6 (19% identical), FUT7 (18% identical), FUT3 (18% identical), FUT4 (18% identical), FUT9 (18% identical).
Diseases named in the same sentence as POFUT3 in open-access papers:
POFUT3 is named in the same sentence as 5 diseases in open-access papers, as found by Europe PMC text mining. Sharing a sentence is not in itself a finding about the gene and the disease.
POFUT3 shares sentences with these, for which no sentence is quoted: cancer (3 papers); artery obstructions (1); coronary artery disease (1); Obesity (1); placental diseases (1).